IL10 (interleukin 10)
Diseases named in the same sentence as IL10 in open-access papers (continued):
Sharing a sentence is not in itself a finding about the gene and the disease.
B-cell lymphoma (continued). "In the present study, we show that IL-10 is critically involved in the development of the CD14+HLA-DRlow/− population in B-cell NHL." (PMID 26230952, 2015). "In the present study, we found that interleukin (IL)-10, which is increased in the serum of patients with B-cell NHL, induced the development of the CD4+HLA-DRlow/− population." (PMID 26230952, 2015). "In the present study, we measured the absolute counts of monocytes and CD14+HLA-DRlow/− cells in the peripheral blood of patients with B-cell NHL and assessed the effect of IL-10 on the development of CD14+HLA-DRlow/− monocytes." (PMID 26230952, 2015). "In a previous study it has been shown that IL-10-polarized M2-like macrophages internalized antibody-coated B cell lymphoma cells." (PMID 24612598, 2014). "IL‐10 is a growth and differentiation factor for B‐cell lymphomas and could be detected in the vitreous fluid of PIOL patients." (PMID 36721307, 2023). "It was noted that high expression of IL-10 mRNA in tumor tissues of patients with aggressive B-cell lymphoma could be an important indicator for prognosis of DLBCL." (PMID 36567775, 2022). "Moreover, treatment of monocytes from B-cell non-Hodgkin lymphoma patients with IL-10 has been shown to decrease human leucocyte antigen–DR isotype (HLA-DR) levels and increase their suppressive capabilities." (PMID 32931721, 2020). "For B cell lymphoma, IL-6 and IL-10 feedback mediate STAT3 constitutive activation." (PMID 31552035, 2019). "In their approach, therapeutic targeting of IL-10 in DCs was carried out using siRNAs codelivered with adjuvant CpG (a TLR9 ligand) and a pDNA-antigen (the idiotype protein of A20 B cell lymphoma) associated with a PLGA-PEI (poly[lactic-co-glycolic acid] and polyethylenimine)-derived microparticle." (PMID 29893623, 2018). "Furthermore, we also found that serum IL-10 levels are elevated in patients with B-cell NHL and serum levels correlate with the absolute number of peripheral monocytes." (PMID 26230952, 2015). "In addition, both are immune suppressive, and we suggest UV-induced immune suppression (mediated by PAF, prostaglandin and IL-10), protects the developing antigenic B cell lymphoma from immune destruction." (PMID 21269511, 2011). "Moreover, IL-10 promotes the growth and differentiation of human B cells and has been shown to promote the growth of B cell lymphomas." (PMID 21269511, 2011). "IL-10 secretion from B cells has been demonstrated in human B cell lymphomas." (PMID 17918201, 2007). "Notably in our study, FIH status did not affect Il10 mRNA expression and the observed tumor suppressive function of FIH is more HIF2α-dependent than HIF1α, suggesting that FIH might suppress B-cell lymphoma via an Il10-independent pathway." (PMID 38422022, 2024). "IL-10 rs1800893 was associated with an increased risk of overall NHL (per-minor-allele odds ratio [ORper-minor-allele]=2.64, 95% confidence interval [CI] 1.75-3.98), B-cell lymphomas (ORper-minor-allele=2.75, 95% CI 1.79-4.23), and DLBCL (ORper-minor-allele=3.03, 95% 1.85-5.01)." (PMID 28060727, 2017). "Most studies on IL-10 in B-cell lymphomas have focused on DLBCL, consistently linking high IL-10 expression with poor prognosis." (PMID 40292253, 2025). "Chronic antigen stimulation and overproduction of cytokines including cellular IL-6 and IL-10 in the HIV-positive patients also plays a potential role in PEL pathogenesis, similar to what occurs in other non-Hodgkin B cell lymphomas." (PMID 33669719, 2021). "Patients with disappearing HDL cholesterol due to B cell lymphoma diffuse large cell lymphoma and ALPS have been noted to have high IL-10 levels and low HDL cholesterol prior to chemotherapy." (PMID 27579193, 2016).
B-cell lymphoma (continued). "We identified IL-10 as being critically involved in the development of CD14+HLA-DRlow/− monocytes and find that IL-10 contributes to the expansion of this subset in B-cell NHL." (PMID 26230952, 2015). "Nevertheless, there is evidence that suggests that rituximab would increase cytotoxic effects of alkylating agents by inhibiting interleukin-10 that results in downregulation of Bcl-2 and sensitization of CD20+ B cells lymphoma to apoptosis." (PMID 23029628, 2012). "However, most research on IL-10 in B-cell lymphoma has concentrated on DLBCL, with limited studies examining the relationship between IL-10 and MZL, another form of non-Hodgkin B-cell lymphoma." (PMID 40292253, 2025). "Decreased expression of miRNA-194 has been demonstrated in Epstein–Barr Virus-infected B cells from patients with post-transplant lymphoproliferative disorder, in turn, overexpression of this miRNA attenuates IL-10 production and increases apoptosis of EBV+ B cell lymphoma lines." (PMID 37894809, 2023). "Here, our results show that NF-κB activated B-cell lymphoma of the LMP1/CD40-expressing mouse model exhibited an immune escape gene signature involving expression of PD-L1 and PD-L2, which expression was co-clusterized with IL-10." (PMID 31382969, 2019). "Notably, the enhanced expression of Tim‐1 resulted in increased IL‐10 production in TK cells but not in other B‐cell lymphoma lines, Raji and Granta 519, suggesting that Tim‐1 augments IL‐10 expression in a PCNSL‐specific cell condition." (PMID 27709813, 2016).
pancreatitis (47 papers, 2006 to 2026). Inflammation of the pancreas. "Apart from the pancreatitis-associated antigens and IL-10-producing FoxP3+ T-regs, CP patients have an increased number of antigen-specific CCR7+CD45RA− central memory T-cells as compared to the healthy and CP-resected controls." (PMID 32796685, 2020). "CP involves a cascade of inflammatory and suppressive events, as demonstrated by the increased number of IL-10+IFNγ−FoxP3+ T-regs against pancreatitis-associated antigens, counteracting the damage caused by cytotoxic cells in CP." (PMID 32796685, 2020). "TNF-α, IL-1β, and IL-10 levels increased significantly (P<0.05) in pancreatitis compared to the control group." (PMID 38333760, 2024). "Experimental data show that IL-10 can be protective and is able to reduce the severity of pancreatitis by limiting pro-inflammation." (PMID 37881430, 2023). "IL-10 is known to have a positive effect on pancreatitis by inhibiting the macrophage release of inflammatory mediators and preventing the development of acinar necrosis." (PMID 35183119, 2022). "IL-10–KO mice have more severe pancreatitis and reduced acinar proliferation in the caerulein–1-day model of AP." (PMID 34847076, 2022). "Because of its antioxidant characteristic, statins can reduce the production of interleukin-10(IL-10), alleviate pancreatitis and fibrosis, and improve exocrine function when applied to the rat model of CP." (PMID 36505827, 2022). "Reportedly, the upregulation of IL-10 in the model of pancreatitis, along with the inhibition of TNF-α, was induced by heme oxygenase-1 (HO1)." (PMID 34122596, 2021). "Cytokine abnormalities, such as elevation of interleukin 1β (IL-1β), IL-6, IL-8, and IL-10, are involved in pancreatitis and IBD." (PMID 32831829, 2020). "Interfering with M2 polarization has been reported to enhance the inflammatory status of macrophages during pancreatitis, and IL-10 production has been shown to impair neutrophil recruitment in inflammatory and infectious conditions." (PMID 29719535, 2018). "In experimental studies, IL-10 has been shown to decrease levels of inflammatory markers and reduce the severity of pancreatitis." (PMID 28751922, 2017). "Regulatory cytokines, such as IL-10, limit the local and systemic consequences of experimental pancreatitis." (PMID 29018453, 2017). "Synthetic IL-10 agonist pretreatment reduced lung injury and mortality from experimental pancreatitis." (PMID 28751922, 2017). "In conclusion, the degree of fibrosis, inflammatory cell infiltration, and the number of BM-derived myofibroblasts were significantly different between IL-10 KO BM and WT BM transplanted mice, highlighting a likely role of IL-10 in pancreatitis." (PMID 27314021, 2016). "IL-10 has been shown to be a potent anti-inflammatory cytokine released during the course of experimental pancreatitis by decreasing the release of proinflammatory factors." (PMID 27314021, 2016). "While plasma IL-6 levels strongly peaked at 3 h, IL-10 further increased to reach maximum levels 24 h after pancreatitis induction." (PMID 23110041, 2012). "When evaluating the systemic inflammatory response following pancreatitis induction, we found both IL-6 and IL-10 plasma levels to be significantly elevated in the BPD-ligated animals at 3 h and these were still enhanced at 48 h." (PMID 23110041, 2012). "In the present study, plasma levels of TNF-α, IL-1ß, IL-6, and IL-10 gradually increased after induction of pancreatitis, with peak levels occurred after 48 or 72 h." (PMID 23029434, 2012). "IL-10 is a potent inhibitor of cytokines and has been shown to attenuate pancreatitis in animal models." (PMID 22396778, 2012). "The initial increase in IL-10 levels is also described in patients after orthopaedic trauma and pancreatitis." (PMID 16899122, 2006). "Therefore, the IL-10-mediated anti-inflammatory effects of poly(I : C)-treated ADSCs were further assessed in a pancreatitis mouse model." (PMID 38550755, 2024).
pancreatitis (continued). "Recent studies have shown that CP is associated with disease-specific regulatory T cell responses, and that the pancreatitis-specific IL-10 response is mediated by IL-10+IFN-γ FoxP3+ regulatory T cells, which are amplified in the blood, bone marrow, and CP lesions." (PMID 36969002, 2023). "5-FU can reduce anti-inflammatory cytokines in pancreatitis, such as IL-10 and TGF-β." (PMID 36110550, 2022). "The importance of pro-inflammatory cytokines in pancreatitis has been highlighted by a recent study in 84 patients with AP who were screened for known polymorphisms in TNFα, interleukin 1 (IL-1), IL-1 receptor antagonist (IL1RN), IL-6, and IL-10." (PMID 30681551, 2019). "Whether BM-secreted IL-10 can attenuate inflammation and fibrosis in pancreatitis and, furthermore, can change the number of myofibroblasts derived from BM is still not known." (PMID 27314021, 2016). "However, SPRC treatment 3 h before the induction of pancreatitis significantly increased both pancreatic and lung IL-10 levels compared to the corresponding values in vehicle treated group." (PMID 22396778, 2012). "Emerging evidence underscores the pivotal role of interleukins (ILs) in pancreatitis pathogenesis across the disease spectrum, encompassing both pro-inflammatory mediators (e.g., IL-1β, IL-6, and IL-8) and anti-inflammatory regulators (e.g., IL-10 and IL-37) 24-26." (PMID 41208897, 2025). "Notably, multiple inflammatory mediators, i.e., IL-17, IL-6 and IL-10 as well as IL-12 and IL-15 have been shown to play a main role in the pathogenesis of pancreatitis, and their serum levels have been reported to correlate with disease severity in AP patients." (PMID 38910880, 2024). "To further elucidate IL‐10′s role in pancreatitis pathogenesis, we established SAP models using IL‐10 knockout (KO) mice." (PMID 40464424, 2025). "Compared with pancreatic cancer, IL-10 concentration increased and IFN-γ levels decreased in CP lesions, suggesting pancreatitis-specific activity of regulatory T cells in situ." (PMID 36969002, 2023). "In experimentally induced pancreatitis, IL-10 levels parallel serum TNF levels and anti-IL-10 treatment reduce lung injury and pancreatic acinar necrosis, as well as reducing mortality from 42% to 0%." (PMID 28751922, 2017). "Specifically, IL-6, IL-8, VEGF, TGF, IL-10 were not only differentially expressed between PDAC and healthy controls but also between PDAC and pancreatitis patients." (PMID 27170998, 2016). "Therapeutic pirfenidone does not ameliorate pancreatitis in IL-10–KO mice or when macrophages are depleted using liposomal clodronate in a well-established model of L-arginine–induced AP." (PMID 34847076, 2022). "Pirfenidone is unable to improve the severity of AP in the absence of IL-10 or depletion of macrophages in the later phases of pancreatitis." (PMID 34847076, 2022). "Accordingly, regulatory T cells, which produce IL-10, attenuate CVB5-induced pancreatitis." (PMID 28973047, 2017). "IL-10 is considered as an anti-inflammatory cytokine; therefore it is reasonable to think that a lack of IL-10 secreted by the BM would result in a more severe pancreatitis." (PMID 27314021, 2016). "Therefore, after GQD intervention, the production of NLRP3 can be inhibited, thereby reducing the synthesis of Caspase-1 and GSDMD, lowering the release of inflammatory factors such as IL-1β and IL-18, and increasing IL-10 levels, thereby preventing the progression of post ERCP pancreatitis." (PMID 40620677, 2025). "Vagotomy did not alter the development of pancreatitis and did not abolish the protective effects of galantamine, as similar to sham surgery controls, galantamine (4 mg/kg-bw) reduced serum amylase levels and increased serum IL-10." (PMID 37907853, 2023).
pancreatitis (continued). "In a caerulein-induced AP mice model, we studied after ITF treatment severity of pancreatitis, the frequencies of infiltrating neutrophils, macrophages, and dendritic cells in the pancreas and colon as well as production of the cytokines TNF-α, IL-1β, and IL-10." (PMID 29018453, 2017). "The origin of IL-10 that suppresses pancreatitis has not been investigated." (PMID 23285260, 2012). "The main production sources of IL-10 are T-helper, monocyte, macrophage, and dendrite cells, and plasma increases IL-10 levels in the organism in the IGF-1 administration without the formation of pancreatitis." (PMID 37763806, 2023). "Galantamine significantly suppressed serum amylase levels and increased serum IL-10 levels in both WT and CD4+/ChATfl/fl mice receiving cerulein, indicating that ChAT expressing T-cells are not required for the protective effects of galantamine in pancreatitis." (PMID 37907853, 2023).
Salmonella Infections (47 papers, 2008 to 2025). Infections with bacteria of the genus SALMONELLA. "Orally administered L. rhamnosus GG improved the production of IL-12 and IL-10 in macrophages and these changes were associated with enhanced resistance to Salmonella infection." (PMID 40141330, 2025). "The anti-inflammatory IL-10 cytokine may be increased to reduce the host tissue damage in response to the inflammation caused by Salmonella infections." (PMID 33822791, 2021). "In addition, the mutants caused more production of IL-10 in HLA-B27 cells than in HLA-A2 cells, indicating that secretion of IL-10 was also affected by HLA-B27 during Salmonella infection." (PMID 22470519, 2012). "Although blocking of IL-10 in vivo and ex vivo led to a better Salmonella infection control in our model, the complex interplay of iron excess and the absence of TIM-3 signalling and their influence on the function of CD4+ CTL warrants further investigation." (PMID 40939292, 2025). "We demonstrate that during iron loading conditions TIM-3 controls IL-10 formation and improves Th1 mediated IFNγ formation leading to better control of Salmonella infection." (PMID 40939292, 2025). "In agreement with the strong decrease of IFNγ we found that the increase of IL-10 on CD4+ T cells in Salmonella infection is time dependent with the highest levels in iron fed Tim3−/− mice." (PMID 40939292, 2025). "IL-10 neutralisation in iron loaded Tim3−/− mice resulted in improved Salmonella infection control and restorage of CD4+ mediated IFNγ formation." (PMID 40939292, 2025). "Let-7 can be downregulated to induce the release of cytokines IL-6 and IL-10 to participate in the regulation of the immune response to Salmonella infection in macrophages." (PMID 35222370, 2022). "The level of TNFα in plasma was significantly higher in the Salmonella infection group compared with the control group, while the level of IL-10 in plasma was significantly lower in the Salmonella infection group compared with that of the control group." (PMID 35163196, 2022). "Subsequent findings in the Salmonella infection model showed that in CD138hi plasma cells, the il10 locus was already primed for transcription." (PMID 33995344, 2021). "Cd72−/− mice display an increased number of LAG-3+CD138hi plasma cells, which produced augmented IL-10 levels following Salmonella infection, leading to impaired control of the bacteria." (PMID 33995344, 2021). "Meanwhile, our results revealed reductions in the expression of other cytokine genes; IL-4 and IL-10, which inhibit host defenses against salmonella infections." (PMID 33396722, 2020). "Meanwhile, other cytokines like IL-4 and IL-10 inhibit the host defenses against salmonella infections." (PMID 33396722, 2020). "Mice pre-treated with the 35624 strain, in a scenario of a Salmonella infection, showed a diminished enterocyte damage and a reduced expression of interleukins IL-8 and IL-10." (PMID 32973728, 2020). "During Salmonella infection IL-35- and IL-10-producing B cells corresponded to plasma cells expressing the transcription factor Blimp126." (PMID 32764544, 2020). "Many studies have indicated that the expression of proinflammatory cytokines such as IFN-γ, IL-6, IL-1β, LITAF, and anti-inflammatory cytokines (IL-10 and transforming growth factor-β4) is regulated in the cecal tonsils by Salmonella infection." (PMID 32054193, 2020). "Despite altered bacterial clearance, control macrophages and butyrate macrophages displayed similar expression of IL1B and TNF mRNA and protein following 3 h of Salmonella infection, whereas IL10 expression was reduced in butyrate macrophages." (PMID 30683619, 2019). "Salmonella-infection increased significantly the secretion levels of M2 MΦ marker IL-10 in Raw246.7 cells." (PMID 30271755, 2018). "We observed that Salmonella counts, phagocytic cell (MDMI and MDMII) counts, and pro- and anti-inflammatory cytokine (TNF-α, HMGB-1 and IL-10) counts increased as Salmonella infection (load) increased." (PMID 27556404, 2016).